CYP2E1 (cytochrome P450 family 2 subfamily E member 1)
Diseases named in the same sentence as CYP2E1 in open-access papers (continued):
Sharing a sentence is not in itself a finding about the gene and the disease.
lung carcinoma (continued). "We report the TiO2-NPs and MWCNTs induced induction in the CYP2E1 specific NDMA-d catalytic activity and significant restoration by two scavenges-DMTU and NAC in human lung cancer cells-A549." (PMID 21980536, 2011). "To investigate whether the CYP2E1 inhibitor is effective on lung cancer, we established the Lewis lung orthotopic xenograft model in WT mice with or without CYP2E1 inhibitor Q11 treatment." (PMID 37875398, 2023).
tuberculosis (19 papers, 2012 to 2026). A chronic, recurrent infection caused by the bacterium Mycobacterium tuberculosis. "Common polymorphisms in CYP2E1 have also been shown to be associated with drug-induced hepatotoxicity in tuberculosis patients." (PMID 40894524, 2025). "A meta-analysis including 1,625 individuals found that people with a high CYP2E1 activity had an increased risk of tuberculosis-drug-induced liver injury compared to those with a low CYP2E1 activity (OR: 1.4, 95% CI: 1.1–1.8)." (PMID 38798770, 2024). "Compared with genotypes including allelic variants, the CYP2E1 rs2031920 variant genotype can lead to higher CYP2E1 activity, resulting in increased levels of hepatotoxic metabolites of anti-tuberculosis drugs (especially isoniazid)." (PMID 34552491, 2021). "Others also revealed that distinct polymorphisms of CYP2E1 might increase the risk of anti-tuberculosis drug-induced hepatotoxicity." (PMID 30131698, 2018). "Four main SNPs in the CYP2E1 gene have been investigated in different populations, including tuberculosis (TB) patients, who often show 1053C>T and 1293G>C mutations, which together form the compound allele CYP2E1*1A, CG; CYP2E1*5, TC." (PMID 23077626, 2012). "Previous studies have reported associations between differential DNA methylation levels in promoter regions of genes encoding metabolic enzymes—such as CYP2E1, CYP2D6, GSTP1, and NAT2—and ATDILI risk in tuberculosis patients." (PMID 40133601, 2025). "Regarding the CYP2E subfamily, the correlation between CYP2E1 gene and anti-tuberculosis DILI is a hot spot." (PMID 34552491, 2021). "CYP2E1 is critical in the hepatotoxicity of tuberculosis drugs which metabolizes isoniazid to reactive oxygen species and diazohydroxide." (PMID 34109203, 2021). "We observed significant associations between the RsaI and 96-bp deletion-insertion SNPs of the CYP2E1 gene and anti-tuberculosis drug-related hepatotoxicity." (PMID 30458875, 2018). "In summary, our meta-analysis indicates that CYP2E1, NAT2 and GSTM1 genetic variation is significantly associated with anti-tuberculosis drug-induced liver injury." (PMID 23082213, 2012). "Elevated CYP2E1 expression is a characteristic feature in tuberculosis-drug-induced liver injury." (PMID 38798770, 2024). "In addition to NAT2, it appears that CYP2E1 and solute carrier organic anion transporter family member 1B1(OATP1B1) coded for by SLCO1B1 gene, could also be important biomarkers for isoniazid-induced liver toxicity in adult patients with tuberculosis." (PMID 26402689, 2015).
non-alcoholic fatty liver disease (18 papers, 2012 to 2025). "CYP2E1 has been implicated in the progression of nonalcoholic fatty liver disease (NAFLD) to its more severe form, nonalcoholic steatohepatitis (NASH), which involves inflammation and fibrosis." (PMID 41323558, 2025). "Many symptoms of non-alcoholic fatty liver disease can be linked to comorbidities, such as obesity, which is the likely source of the reduction in cardiac output and CYP2E1 activity and expression seen in non-alcoholic fatty liver disease." (PMID 39574200, 2024). "In non‐alcoholic fatty liver disease, USP14 stabilises HSP90AA1 through deubiquitination, leading to increased levels of CYP2E1 and further exacerbating disease progression." (PMID 40988122, 2025). "By the regulation of HO-1, CYP2E1, and ROCK/NF-κB signaling, PF can improve non-alcoholic fatty liver disease." (PMID 36500627, 2022). "Cytochrome P450 2E1 (CYP2E1) is a key target protein in the development of alcoholic and nonalcoholic fatty liver disease (FLD)." (PMID 33604316, 2021). "Despite the recognized importance of CYP2E1 in the pathogenesis of the alcoholic and nonalcoholic fatty liver disease (FLD), where HCC is the final stage, CYP2E1 has not yet been evaluated as a pharmacological target." (PMID 33604316, 2021).
liver cancer (17 papers, 2017 to 2025). An epithelial or non-epithelial malignant neoplasm that arises from the liver. "Chronic alcohol increases the risk of liver cancer and mechanisms might include increased induction of acetaldehyde, CYP2E1, and ROS formation." (PMID 35269779, 2022). "Notably, NDMA is metabolized in the liver by CYP2E1 to methyl diazonium, leading to mutations caused by methylation and the development of liver cancer." (PMID 36231768, 2022). "The example provided in Box 3 focuses on the AOP “Inhibition of the mitochondrial complex I of nigro-striatal neurons leads to parkinsonian motor deficits”, while the example shown in Box 4 is related to the AOP “Cyp2E1 Activation Leading to Liver Cancer”." (PMID 40896731, 2025). "Diethylnitrosamine induces liver injury and hepatocarcinogenesis due to the metabolic activation by CYP2E1, which strongly correlates with the incidence and severity of liver cancer." (PMID 39682707, 2024). "As per these previous studies, the CYP2E1 gene expression decrease found in our study agrees with the formation of large tumor sizes, the severity of liver cancer, and a lower survival rate (62.5%) when compared to the CTL group." (PMID 37176094, 2023). "The third case study focused on carcinogenicity and the AOP on “Cyp2E1 Activation Leading to Liver Cancer” (AOP 220 in the AOP-Wiki)." (PMID 35211660, 2022). "CYP2E1-mediated ethanol metabolism generates oxidative stress leading to DNA damage, a pathway to alcohol-related development of liver cancer." (PMID 35269779, 2022). "AOP 220 presents the chronic CYP2E1 activation (MIE) leading to liver cancer, which induces a series of cascade events." (PMID 35211660, 2022). "Oxidative stress (KE1) caused by CYP2E1 activation can induce hepatotoxicity (KE2), leading to liver cancer." (PMID 35211660, 2022). "Moreover, in the mouse models of liver cancer, CYP2E1 inhibitors not only reduced the incidence and size of tumors but also significantly decreased the expression of FGL2." (PMID 35136014, 2022). "Their results suggest that the differential expression of CYP2E1 may play an important role in the occurrence of liver cancer." (PMID 36613552, 2022). "Moreover, using a liver cancer cell (HepG2 cells) model, our group has recently shown that nitriles are less cytotoxic compared to ITCs; however, like ITCs, nitriles do have genotoxic potential that is further increased by CYP2E1 overexpression." (PMID 28690627, 2017).
alcoholic steatohepatitis (15 papers, 2010 to 2025). "Elevated enzymatic activity of CYP2E1 is critically responsible for the development of alcoholic steatohepatitis (ASH) due to the excessive production of ROS during ethanol metabolization." (PMID 36555703, 2022). "In conclusion, the treatment of alcohol fatty liver disease with PCP mainly exerted anti-inflammatory effects by inhibiting CYP2E1 to attenuate the release of endotoxin and inhibiting MyD88/TLR4/NF-κB signaling pathway." (PMID 33014105, 2020). "In summary, the treatment of alcohol fatty liver disease with PCP exerted antioxidant effects by inhibiting the increase of CYP2E1 and influencing the expression of relevant oxidative stress factors through the KEAP-1/Nrf2-HO-1 signaling pathway." (PMID 33014105, 2020). "One of key pathways in alcoholic steatohepatitis appears to be the induction of CYP2E1 by ethanol." (PMID 28951767, 2017). "Moreover, recent studies showed that chemical inhibition of CYP2E1 and other alcohol metabolizing enzymes reduces alcoholic steatohepatitis by decreasing triglyceride accumulation and proinflammatory cytokine levels in liver." (PMID 20814553, 2010). "Further studies have shown ROF’s ability to suppress alcoholic fatty liver disease by maintaining the antioxidant balance in hepatocytes, upregulating GSH and SOD, downregulating CYP2E1 and TLR4, and decreasing the phosphorylation of NF-κB." (PMID 40689212, 2025).
Hepatitis (14 papers, 2013 to 2025). Inflammation of the liver. "Halogenated anesthetics can induce hepatitis in susceptible persons, and cytochrome p4502E1 (CYP2E1) enzymes responsible for their metabolism induce antibodies in addition to hepatitis." (PMID 30305319, 2018). "Some studies have shown the relationship between the CYP2E1 RsaI c1/c1genotype and the risk of anti-TB drug-induced hepatitis." (PMID 24465778, 2014). "In recent years, genetic polymorphisms of NAT2, CYP2E1 as well as GSTs have gained more focus by linking patient’s genetic susceptibility to anti-TB drug-induced hepatitis." (PMID 23460870, 2013). "In the present study, 6 tSNPs were selected using Haploview 4.2 based on the HapMap database of Han Chinese in Beijing and evaluated the association between these genetic variants in CYP2E1 and the risk of anti-TB drug-induced hepatitis." (PMID 23460870, 2013). "As we know, this is the first study to explore association between tSNPs of CYP2E1 and anti-TB drug-induced hepatitis in Chinese TB patients." (PMID 23460870, 2013). "No tagging single-nucleotide polymorphisms (tSNPs) of cytochrome P450 2E1(CYP2E1) in the risk of anti-TB drug-induced hepatitis have been reported." (PMID 23460870, 2013). "This is the first exploration of an association between tSNPs of CYP2E1 and anti-TB drug-induced hepatitis in Chinese TB patients." (PMID 23460870, 2013). "AcHz can be converted either to relatively non-toxic diacetylhydrazine, or a reactive intermediate metabolite through CYP2E1, which may cause toxic hepatitis." (PMID 35928262, 2022). "Even so, it is important to identify CYP2E1 epitopes because these epitopes can be utilized to develop specific diagnostic tests or to predict individuals at risk for developing drug or virus-induced hepatitis." (PMID 30305319, 2018). "We hypothesized that CYP2E1 epitopes associated with different types of hepatitis may be shared and may impact immune responses and metabolism." (PMID 30305319, 2018). "Among several CYP2E1 genetic polymorphisms, only the RsaI/PstI (rs2031920/rs3813867) and DraI (rs6413432) polymorphism have been evaluated in association with anti-TB drug-induced hepatitis." (PMID 23460870, 2013). "Polymorphisms of the genes encoding CYP2E1 may influence the activity of enzyme as well as the susceptibility to anti-TB drug-induced hepatitis." (PMID 23460870, 2013). "Therefore, PXR could increase the production of hydrazine, free radical hepatotoxins, and thus the risk of INH-induced hepatitis, through P450 oxidase and CYP2E1." (PMID 26091473, 2015). "In BCG-induced liver inflammation, CYP2E1 expression, along with NF-κB, and MAPK pathway activity, exhibited dynamic changes." (PMID 40531979, 2025). "Using this optimized method, we found that CYP2E1 metabolic activity was reduced in BCG-induced hepatitis." (PMID 41171730, 2025). "During the progression of hepatitis and hepatocellular carcinoma, CYP2E1 undergoes remodeling and actively participates in pathological processes." (PMID 41171730, 2025). "Using a BCG-induced male rat hepatitis model, we investigated the dynamic changes in CYP2E1 metabolic activity at different stages of hepatitis and explored the underlying mechanisms." (PMID 40531979, 2025). "Prior work has confirmed that rats in the hepatitis group exhibit reduced hepatic CYP2E1 protein expression, metabolic activity, and transcriptional levels compared with control rats." (PMID 41171730, 2025). "This study aims to enhance the understanding of CYP2E1 regulation and identify potential therapeutic targets and strategies for the treatment of hepatitis." (PMID 40531979, 2025). "Previous studies conducted by our team have demonstrated that CYP2E1 expression is downregulated during Bacillus Calmette-Guérin (BCG)-induced immune liver injury (hepatitis)." (PMID 40531979, 2025).
Hepatitis (continued). "Results showed that CYP2E1 metabolic activity in BCG-induced hepatitis was reduced to half that of the control group (calculated by area under the curve), indicating impaired metabolic function." (PMID 41171730, 2025). "Beyond genetic regulation, diseases like hepatitis can profoundly disrupt CYP2E1 expression and activity." (PMID 41171730, 2025). "It has been studied in detail that exposure to some chemicals induces the production of serum anti-CYP2E1 antibodies involved in the pathogenesis of hepatitis, especially halothane hepatitis." (PMID 35763063, 2022). "The consumption of unsaturated fatty acid, especially linoleic acid, increased cytochrome P450 2E1 (CYP2E1) activity, damaged intestinal barrier, and induced liver inflammation." (PMID 34109203, 2021). "One epitope (Gly113-Leu135) induced hepatitis and CYP2E1 autoantibodies in mice after modification of Lys123 (P < 0.05)." (PMID 30305319, 2018). "Reduced hepatitis and CYP2E1 autoantibodies in IL-4-deficient mice, as well as the detection of CYP2E1 IgG4 subclass autoantibodies in patients with anesthetic hepatitis, support a role for IL-4 in the development of CYP2E1 autoantibodies and hepatitis." (PMID 30305319, 2018). "In BALB/c mice, Gly113-Leu135 triggers hepatitis as well as CYP2E1 antibodies after modification of Lysine123 (Lys123) with TFA." (PMID 30305319, 2018). "Candidate epitopes were tested for induction of hepatitis and CYP2E1 autoantibodies in mice and recognition by sera from patients with anesthetic drug-induced and viral hepatitis." (PMID 30305319, 2018). "We found a novel CYP2E1 epitope that was detected in anesthetic and viral hepatitis and that triggered hepatitis in mice." (PMID 30305319, 2018). "Together these data indicate that inhibition of AR alleviates the MCD diet-induced liver inflammation and fibrosis in db/db mice, probably through dampening CYP2E1 mediated-oxidative stress and ameliorating the expression of pro-inflammatory cytokines." (PMID 24066058, 2013). "Furthermore, an immune-mediated liver injury model was established through intravenous injection of Bacillus Calmette-Guérin (BCG) to investigate the dynamic changes in CYP2E1 across different stages of hepatitis and elucidate its regulatory mechanisms." (PMID 40531979, 2025). "During acute hepatitis, CYP2E1 activity is significantly impaired, with a slower recovery of protein expression, highlighting the importance of restoring hepatic metabolic function as part of hepatitis treatment." (PMID 40531979, 2025). "CYP2E1, an isozyme of the drug-metabolizing enzyme cytochrome P450 (CYP), mostly oxidizes volatile hydrocarbons such as TCE and can be an antigen to produce anti-CYP2E1 autoantibodies that cause hepatitis." (PMID 35763063, 2022). "We show that posttranslational modification of Lys123 in JHDN-5 is required to induce hepatitis and CYP2E1 autoantibodies in BALB/c mice, confirming earlier hypotheses described in halothane toxicity." (PMID 30305319, 2018). "We had previously shown that the model develops hepatitis and CYP2E1 autoantibodies." (PMID 30305319, 2018). "CYP2E1 antibodies detected in anesthetic hepatitis patients have been detected in patients with viral hepatitis, suggesting that these different forms of hepatitis could develop immune reactions to a common segment or epitope of CYP2E1." (PMID 30305319, 2018). "Thus, our findings support our idea that JHDN-5 is a promising CYP2E1 epitope in drug-induced hepatitis and is recognized by I-Ed." (PMID 30305319, 2018). "Cytochrome p4502E1 (CYP2E1) autoantibodies are biomarkers for drug-induced hepatitis and chronic hepatitis C. However, major histocompatibility-restricted CYP2E1 epitopes associated with these diseases have not been identified." (PMID 30305319, 2018). "Even so, detecting CYP2E1 autoantibodies in all three forms of hepatitis suggests that a common CYP2E1 epitope may be responsible." (PMID 30305319, 2018).
Hepatitis (continued). "So far, no tagging single-nucleotide polymorphisms (tSNPs) of CYP2E1 in the risk of anti-TB drug-induced hepatitis have been reported." (PMID 23460870, 2013). "And in other countries, all studies reported negative results about relationship between CYP2E1 genetic polymorphisms and anti-TB drug-induced hepatitis." (PMID 23460870, 2013). "However, the dynamic changes in CYP2E1 metabolic activity during the acute, chronic, and recovery phases of hepatitis remain unclear." (PMID 40531979, 2025). "However, CYP2E1 epitopes that trigger autoantibodies or hepatitis are unknown, and their role in disease pathogenesis is unclear." (PMID 30305319, 2018). "Thus, our findings support JHDN-5 as a CYP2E1 epitope that may also be responsible for hepatitis or CYP2E1 autoantibodies in AH patients and suggest that this epitope could be the dominant CYP2E1 epitope in anesthetic hepatitis." (PMID 30305319, 2018). "Reduced CYP2E1 enzyme activity has been reported in alcoholic hepatitis, and these patients can express CYP2E1 autoantibodies; however, in alcoholic hepatitis, reduced CYP2E1 activity has been associated with increased severity of hepatitis and not the antibody itself." (PMID 30305319, 2018). "We propose that posttranslational modification of JHDN-5 induces hepatitis and JHDN-5 IgG4 and that these JHDN-5 autoantibodies inhibit CYP2E1 enzymatic activity." (PMID 30305319, 2018). "IL-4−/− mice immunized with TFA-JHDN-5 developed significantly less hepatitis and TFA and CYP2E1 autoantibodies than did BALB/c mice, suggesting that IL-4 promotes TFA-JHDN-5-induced hepatitis and antibodies, a finding similar to that in our prior studies." (PMID 30305319, 2018). "Hepatitis histologic scores (p<0.05); TFA, S100, and CYP2E1 IgG1 antibody levels; and S100 and CYP2E1 IgG2a antibody levels were lower in IL-6−/− mice than in BALB/cBy mice." (PMID 23577207, 2013). "TFA-JHDN-5 immunizations induced significantly more hepatitis, serum levels of TFA antibodies, CYP2E1 autoantibodies, and hepatic tissue levels of interleukin (IL)-1β, IL-2, IL-4, IL-5, IL-6, IL-17, interferon (IFN)-γ, and tumor necrosis factor (TNF)-α by 3 weeks." (PMID 30305319, 2018). "Even so, without knowing CYP2E1 immunogenic epitopes, the significance of posttranslational modification of CYP2E1 in hepatitis or CYP2E1 autoantibodies may be underestimated." (PMID 30305319, 2018).